MPO (myeloperoxidase)
Diseases named in the same sentence as MPO in open-access papers (continued):
Sharing a sentence is not in itself a finding about the gene and the disease.
cancer (continued). "In consideration of the recently published studies and the absence of a new systematic and comprehensive evaluation for the association between MPO-463G > A polymorphism and cancer risk, we conducted this meta-analysis to shed a light on this relationship." (PMID 28764808, 2017). "In cumulative analysis, the stable trend indicated that evidence was sufficient to show the association between MPO-463G > A polymorphism and cancer risk." (PMID 28764808, 2017). "This meta-analysis suggested that MPO-463G > A polymorphism was associated with the overall reduced cancer susceptibility significantly." (PMID 28764808, 2017). "Tumorigenesis was multifocal and characterized by extensive infiltrates of myeloperoxidase-positive neutrophils otherwise implicated in cancer progression in humans and animal models." (PMID 25831236, 2015). "Individuals with MPO polymorphism –463G→A in the promoter region, which reduces MPO expression, have decreased risk for various cancers." (PMID 21859636, 2012). "Because tissue damage triggered by inflammatory mediators is associated with cancer establishment, we evaluated MPO and ELA activity in the chemically treated tissue samples." (PMID 23176085, 2012). "If this is the case, then deploying an MPO inhibitor during cancer chemotherapy could be a practical way of reducing associated toxicities." (PMID 38531625, 2024). "Neutrophil‐derived MPO has been implicated in cancer development and progression." (PMID 38923838, 2024). "This prospective, randomized, single-center trial aimed to assess the impact of anesthesia techniques and drugs on serum expression of NETosis markers (H3Cit, MPO, and NE), as well as other markers implicated in cancer dissemination (MMP-9 and VEGF-A) at 3 h post-surgery." (PMID 38678209, 2024). "Notably, a comprehensive meta‐analysis of 16 858 cases of genetic MPO deficiency and 21 756 control subjects revealed that lower MPO expression is associated with an overall reduced cancer risk in both solid and haematological cancers." (PMID 37699574, 2023). "Therefore, MPO expression is tightly regulated in a lineage-specific manner and dysregulation of its expression has been linked to multiple diseases, including cancer and neurodegenerative disorders." (PMID 33916434, 2021). "In addition to gene polymorphism, MPO induces cancer through the activation of genotoxic intermediates and procarcinogens through an indirect implication of MPO." (PMID 29669993, 2018). "Furthermore, risks of the development of cancer are directly linked to the endogenous production of high MPO levels." (PMID 29669993, 2018). "MPO is associated with increased risk for various cancers, including lung adenocarcinoma." (PMID 28448444, 2017). "Besides, in view of the cumulative analysis results, we intended to draw a conclusion that MPO-463G > A polymorphism had a protective significance of cancer risk." (PMID 28764808, 2017). "By damaging the DNA of host cells, MPO-induced DNA halogenation might contribute to the association between chronic inflammation and cancer." (PMID 21859636, 2012). "There is accumulating evidence has implicated MPO in the pathophysiology of different diseases besides cardiovascular disease, including rheumatoid arthritis, kidney disease, pulmonary fibrosis, Alzheimer’s disease, Parkinson’s disease, multiple sclerosis, liver diseases cancer." (PMID 35326206, 2022). "MPO-generated HOCl can cause structural changes, strand breaks and impact DNA binding properties, thereby leading to DNA irregularities, which ultimately may promote cancer progression." (PMID 36293108, 2022). "Whether MPO-463G > A polymorphism could be a good predictor of cancer remained controversial." (PMID 28764808, 2017). "Interestingly, MPO+ cell infiltration was higher in MMR-deficient than in MMR-proficient CRC as previously suggested by a study conducted with 67 samples from a limited number of cancers (n = 35)." (PMID 23734221, 2013).
cancer (continued). "Hypochlorous acid (HOCl), an important reactive oxygen species generated by myeloperoxidase (MPO), is widely involved in the pathogenesis of various conditions, including cardiovascular, renal, and neurodegenerative diseases, as well as cancer." (PMID 42293748, 2026). "Co-IF staining for H3cit and MPO revealed that Tph1 KD in NEPC organoids led to suppressed hepatic NET formation in nearby areas of metastatic cancer cells compared with scrambled shRNA–transfected counterparts." (PMID 39903533, 2025). "In cancer cells, they regulate myeloperoxidase (MPO), which increases the oxidative stress and leads to apoptosis or necrosis." (PMID 40509281, 2025). "MPO is a peroxidase that has received increasing interest as a potential therapy target in cancer patients." (PMID 40652059, 2025). "The downregulation of MPO seemingly has an anti-inflammatory effect that inhibits the growth of cancer cells, which aligns with the results of our cell viability measurements but does not explain the higher ROS production observed upon treatment." (PMID 41011284, 2025). "For early prediction of cardiotoxicity in cancer patients, blood levels of N-terminal pro-B-type natriuretic peptide (NT-proBNP) and myeloperoxidase (MPO) can be measured." (PMID 40459761, 2025). "Using fluorescent immunostaining of MPO-positive neutrophils, their localization in cancer cells and stromal tissue areas was compared." (PMID 39904796, 2025). "The study aimed to prospectively investigate the clinical value of interleukin-6, myeloperoxidase, and tumor necrosis factor alpha as potential biomarkers of cancer therapy-related cardiac dysfunction (CTRCD) in patients receiving anthracycline treatment." (PMID 40362309, 2025). "An increasing MPO+ cell pattern has been shown to rise from normal mucosa to carcinoma progressively." (PMID 40149674, 2025). "Increased MPO levels in cancer patients are thought to correlate with disease activity and poor prognosis, especially among myeloid malignancies and solid tumors." (PMID 39810847, 2024). "Increased levels of MPO have been found in biological samples of cancers, such as serum from lung cancer patients, plasma from subjects with gynecologic cancer, the neoplastic tissue of colon tumors, and so on." (PMID 38275657, 2024). "In contrast, normal pancreas tissue (including normal pancreas tissue and cancer adjacent pancreas tissue) demonstrated minimal MPO staining." (PMID 38367056, 2024). "In a clinical study, clusters of CD68/CD163+ macrophages, CD4+ lymphocytes, CD3+ T lymphocytes, and myeloperoxidase (MPO)-positive neutrophils were significantly increased in the ovarian cortex of cancer patients after chemotherapy." (PMID 38942605, 2024). "MMP-9 and MPO are components of NETs present on externalized nuclear DNA that promote endothelial cell and cancer cell proliferation." (PMID 38730718, 2024). "The current work strengthens existing data generated in a non-cancer inflammatory model to suggest that Scl1 on GAS cells is a potent NET inhibitor through reduction in MPO activity." (PMID 38515758, 2024). "NETs can be mixed with granules and cytoplasmic components such as neutrophil elastase (NE), citrullinated histone H3 (CitH3), and myeloperoxidase (MPO) to fight infections or cancer burden." (PMID 38491551, 2024). "This study focuses on how Soluble P Selectin, NET, and MPO affect DVT in platinum-based chemotherapy with various types of cancer." (PMID 39810847, 2024). "MPO is necessary for the release of extracellular neutrophil (NET) traps, which have been associated with cancer progression in several preclinical models." (PMID 37513924, 2023). "In this context, growing evidence shows the involvement of MPO in the pathophysiology of different diseases, including cancer." (PMID 37627581, 2023). "Cancer cells displayed a greater tendency to avoid neutrophils and M1-like MDMs as the density of MPO+ macrophages increased." (PMID 36725935, 2023).
cancer (continued). "We have previously reported new biological roles for MPO as a key regulator of fibrosis and angiogenesis, which contribute to cancer development and progression." (PMID 37699574, 2023). "In recent years, the role of MPO in cancer has received attention, despite being a relatively new area of research." (PMID 37627581, 2023). "LPS challenge eliminated sevoflurane-induced cancer growth, increased MPO and CCR2 expression and neutrophil infiltration, and reduced pan macrophage infiltration." (PMID 35953652, 2023). "Therapeutic targeting of MPO has recently gained considerable attention in a number of disease states, including cancer." (PMID 37699574, 2023). "Some of the functions of MPO in cancer cells were abolished by using an MPO inhibitor or by blocking the internalization of the enzyme into the cells." (PMID 37627581, 2023). "Consistently, HRG overexpressed cancer cell CM reduced the MPO activity and the number of neutrophils and the MPO activity of neutrophils treated with HRG knockdown cancer cell CM was higher." (PMID 37254661, 2023). "It has been shown that MPO contributes directly or indirectly to many other diseases, but the most dangerous is cancer." (PMID 37513924, 2023). "The addition of neutrophils or MPO further enhanced the accumulation of ROS in cancer cells, and the addition of MPO reduced the viability of mouse and human PDAC cell lines." (PMID 36813961, 2023). "MPO bound to the surface of A549 cells after 5 min of exposure, indicating a rapid uptake by cancer cells." (PMID 37627581, 2023). "NE and MPO are the critical compositions of NETs, and mouse models lacking NE have been utilized to study the effects of decreased NETs on cancer metastasis and sepsis." (PMID 37188184, 2023). "In conclusion, our results demonstrate that MPO can directly alter cancer cell function in vitro, in a mechanism involving both binding to the cell surface and enzymatic activity." (PMID 37627581, 2023). "Circulating levels of NET components, such as cell-free DNA (cfDNA), neutrophil elastase (NE)–DNA, myeloperoxidase (MPO)–DNA, and citrullinated histone H3 (CitH3) can serve as beneficial biomarkers for several kinds of cancers." (PMID 37300897, 2023). "Overall, evidence from this study further supports the utility of MPO as a promising predictor of cancer therapy-induced cardiotoxicity, even at a baseline level." (PMID 37444400, 2023). "With regard to the potential limitations of established cardiac biomarkers in cancer-therapy-related cardiotoxicity, galectin-3 and MPO are currently under investigation for their use in the early detection of cardiotoxicity." (PMID 36551214, 2022). "MPO also plays important roles in neuroinflammation and cancer, which we will elaborate upon in the following sections." (PMID 36293108, 2022). "MPO, an enzyme abundantly expressed in neutrophil granulocytes, is upregulated and secreted by TANs in several cancer types." (PMID 35328639, 2022). "The following meta-analysis aimed to determine the role of MPO in the monitoring of cancer-therapy-related cardiotoxicity." (PMID 36551214, 2022). "At the initial stage of cancer treatment, the median measured time was 3 months (range: 0.5–3 months), and the meta-analysis results reveal that MPO levels serve as an earlier marker of cardiotoxicity compared with TnI and NT-proBNP levels." (PMID 36551214, 2022). "We further discuss MPO interactions with barrier forming endothelial and epithelial cells, specialized cells of the central nervous system (CNS) and its involvement in cancer progression." (PMID 36293108, 2022). "Using two-color immunofluorescence analyses, we observed variability regarding the co-localization of CD66b and MPO between patients, indicating the heterogeneous population of neutrophils in cancer." (PMID 35386697, 2022). "The heterogeneity is lower (I2: 21%) than in the analysis of changes of MPO levels in response to cancer therapy." (PMID 36551214, 2022).
cancer (continued). "Mean MPO levels were higher in patients upon the administration of cancer therapy [SMD 0.58 (90% CI 0.35, 0.80), I2: 56%, p = 0.08]." (PMID 36551214, 2022). "As has been discussed in previous sections, MPO is required for NET release and NETs have been linked to cancer progression in several preclinical models." (PMID 36293108, 2022). "Neutrophil-dependent cancer progression is known to occur through the elaboration of reactive oxygen species, myeloperoxidase (MPO), and the programmed death receptor 1 (PD-1)/programmed death receptor ligand 1 (PD-L1) axis, among other mechanisms." (PMID 35267667, 2022). "In previous studies, we have already described the decrease of MNR and the increase of NE and MPO in cancer plasma, as compared to healthy individuals." (PMID 36443816, 2022). "In this systematic review and meta-analysis, we assessed the value of galectin-3 and MPO in monitoring cardiotoxicity in cancer patients." (PMID 36551214, 2022). "The present meta-analysis highlights MPO as a promising biomarker of cancer-therapy-related cardiotoxicity, whereas the available evidence does not yet consistently support a beneficial role for galectin-3, potentially due to significant heterogeneity." (PMID 36551214, 2022). "MPO is involved in early stages of cancer development and has been proposed to influence the TAN–TAM axis." (PMID 35328639, 2022). "According to the findings of our meta-analysis, MPO levels were noticeably increased in patients following cancer treatment." (PMID 36551214, 2022). "Collectively, these studies demonstrate a major mechanism, where reactive oxidants generated by MPO can promote cancer progression." (PMID 36293108, 2022). "Patients with high MPO levels (422.6 pmol/L) 3 months into cancer treatment had a 36.1% chance of developing CTRCD by 15 months." (PMID 34859069, 2021). "Levels of MDA, and P. carbonyl and MPO activity increased significantly in the cancer group (HCC) and were accompanied by a decrease in the activity of CAT and SOD enzymes." (PMID 35177980, 2021). "Surprisingly, H3Cit in the plasma of cancer patients did correlate with activators or products of NETs, such as MPO, NE, IL-8, and IL-6." (PMID 34503307, 2021). "ET-1 and MPO are also, by now, the only two (inflammatory) biomarkers with a proven role in predicting cardiotoxicity from cancer drugs." (PMID 34202603, 2021). "In sharp contrast, in recurrent cancer biopsies, there was a significant correlation with the expression of CD66b, IL-17, MPO, and CXCR4." (PMID 34830938, 2021). "G-CSF that is produced by most types of cancer cells activates neutrophils and stimulates them to NET formation, whereas some NET components like myeloperoxidase, proteinases and histones, can have a cytotoxic impact on cancer cells and inhibit cancer growth." (PMID 33435568, 2021). "Based on the cancer-inflammation relationship, the effect of BcAEF on the migration and/or activation of neutrophils was assessed by determining myeloperoxidase activity (MPO)." (PMID 32899132, 2020). "Some NET components, including myeloperoxidase, proteinases and histones, can have a cytotoxic impact on cancer cells and inhibit cancer growth." (PMID 31297037, 2019). "Cancer progression advances by the biochemical alterations of different biomolecules and genes by various oxidative species, ultimately produced through MPO." (PMID 29669993, 2018). "In line with this, we found clear correlations between neutrophil activation, MPO-DNA complexes and plasma levels of H3Cit in cancer patients." (PMID 29324871, 2018). "The knowledge of the precise biochemical relationship between the inflammatory response and specific malignancy is a vast field to be understood, although growing evidence points to links between the relationships of MPO, inflammation, and cancer." (PMID 29669993, 2018).
cancer (continued). "Though a number of studies have been conducted to explore the association between myeloperoxidase (MPO)-463G > A polymorphism and cancer risk, the results remain inconsistent." (PMID 28764808, 2017). "Mean number of infiltrating MPO positive cells in primary and recurrent cancer biopsies were 16.6 (±21.6) and 19.0 (±34.8), respectively." (PMID 27531373, 2016). "In cancer adjacent tissues, E-cadherin degradation is prominent, which correlates with the level of MPO protein expression." (PMID 27412620, 2016). "Twelve out of 47 and 10 out of 45 displayed a high MPO cell density in primary and recurrent cancer biopsies, respectively." (PMID 27531373, 2016). "MPO activity was lower in BAL fluid in cancer septic mice compared to previously healthy septic mice." (PMID 27018973, 2016). "MPO and IL-17 positive immune cells correlated significantly in biopsies of primary and recurrent carcinomas (rs = 0.41; p = 0.004 and rs = 0.40; p = 0.007, respectively)." (PMID 27531373, 2016). "Neutrophil Elastase (ELA) and Myeloperoxidase (MPO) have also been directly or indirectly related to the cancer immunoediting and metastasis." (PMID 25268644, 2014). "The myeloperoxidase gene is taking role in anti-apoptosis process where cancer cells kill themselves." (PMID 23777239, 2013). "To assess the broader relevance of MPO, we performed Cox regression across 33 TCGA cancer types." (PMID 40547041, 2025). "While markers like H3Cit and MPO-DNA may have prognostic value in cancer patients and indicate NET formation, their ability to predict treatment response is limited." (PMID 40801632, 2025). "First, two subjects in the MPO and three on the CG were lost due to cancer relapse." (PMID 41395600, 2025). "HOCl is the main oxidation product of MPO in vivo, and researchers have found that apoptosis could be induced by inhibiting the chlorination of MPO and thus reducing HOCl levels, implying a new anti-cancer strategy by targeting HOCl." (PMID 38275657, 2024). "The validation of MPO as a key gene and its potential role as a protective factor in PCa further highlights the importance of these key targets and their metabolic pathways in cancer biology." (PMID 39834542, 2024). "Furthermore, MPO has been described as a key enzyme in carcinogenesis, as well as in the progression of cancer." (PMID 38530585, 2024). "We and others have demonstrated an increase in MPO in myeloid cells in the presence of cancer." (PMID 38367056, 2024). "Accordingly, we aimed to determine whether MPO can also influence cancer cell function and its mechanism of action." (PMID 37627581, 2023). "In particular, neutrophil-derived MPO may make a meaningful impact on cancer development and progression 50.Therefore, we utilized SYSUCC data to confirm that high MPO levels were associated with a poor prognosis for CRC." (PMID 37935721, 2023). "Specifically, calprotectin and MPO are also expressed, to a lesser extent, in monocytes, macrophages or eosinophils; and cfDNA and nucleosomes can be released by apoptotic or necrotic cells present in cancer patients." (PMID 36817483, 2023). "Several studies have noted the involvement of MPO in the regulation of cancer." (PMID 37627581, 2023). "We observed that MPO promoted the proliferation of cancer cells and inhibited their apoptosis." (PMID 37627581, 2023). "Effects of MPO on cancer cell function could be reduced when MPO uptake was blocked with heparin or upon inhibition of the enzymatic activity with the MPO inhibitor 4-aminobenzoic acid hydrazide (4-ABAH)." (PMID 37627581, 2023). "Higher densities of MPO+ macrophages were also associated with increased interactions between endothelial cells and M1-like MDMs with T cells, concomitant with reduced interactions between M2-like MDMs and CD8+ T cells, which can be immunoregulatory in cancer." (PMID 36725935, 2023). "Previous studies in pan‐cancer indicated that H3Cit and MPO were effective prognostic markers." (PMID 38018346, 2023).